LONP1 (lon peptidase 1, mitochondrial)
Diseases named in the same sentence as LONP1 in open-access papers (continued):
Sharing a sentence is not in itself a finding about the gene and the disease.
cancer (continued). "Here, we identified the specific target substrates of each protease and discovered functional crosstalk through which LONP1 and ClpP cooperatively modulate aspects of mitochondrial proteostasis that are crucial for cancer cell growth and survival." (PMID 33637676, 2021). "Here, we demonstrated that LONP1 and ClpP work together to maintain mitochondrial proteostasis in cancer." (PMID 33637676, 2021). "Considering the pro-survival roles of LONP1 and ClpP, we next evaluated LONP1- and ClpP-mediated mitochondrial protease requirements for cancer cell adaptation to metabolic stressors, such as starvation and oxidative stress." (PMID 33637676, 2021). "Particularly, emerging studies suggest that LonP1 and ClpXP are needed to alleviate mitochondria stress and promote cancer cell survival and metastasis in a subset of solid and hematology malignancies." (PMID 33922062, 2021). "Together, these findings further indicate a link between LONP1 and ClpP function in cancer cell proliferation and viability." (PMID 33637676, 2021). "CDDO, in the micromolar range, induces caspase-dependent apoptosis in several human cancer cells with high LonP1 expression, comprising colon carcinoma, B-cell lymphoma, breast ductal carcinoma, and liver hepatocellular carcinoma." (PMID 33922062, 2021). "Accordingly, inhibition of both LONP1 and ClpP potently reduced cancer cell viability with concomitantly induced mitochondrial bioenergetics dysfunction as evidenced by phosphorylation of AMPK and activation of autophagy." (PMID 33637676, 2021). "In contrast, while inhibition of other proteases such as LONP1 kills cancer cells, homozygous deletion of Lonp1 is embryonic lethal in mice." (PMID 33037181, 2020). "LONP1 is upregulated in different types of cancer, and its upregulation makes cancer cells resistant to new environmental conditions, such as hypoxia, typical of malignant tumors." (PMID 32521756, 2020). "In previous studies, CDDO-Me and LONP1 siRNA induced apoptosis of various cancer cells that have potent proliferative and differentiating abilities by inhibiting mitochondrial functionality." (PMID 31387295, 2019). "Lonp1 is a major regulator of mitochondrial homeostasis, for which downregulation in cancer cells is known to induces massive caspase 3 activation and apoptotic death." (PMID 31061415, 2019). "Out of 9 classifiers based on mtFE scores, 4 proteins (i.e. Lonp1, Sod1, Txn2 and Ogdh) were identified as potential cancer drivers in a forward genetic screen in mice, in comparison with 1 and 3 in mito and lysate data, respectively." (PMID 31061415, 2019). "While previous studies regarding LonP1 and cancer reported that LonP1 induced EMT through ROS-dependent MAPK signaling, at least in 293 T cells, we found that mitochondrial ROS were not implicated in EMT induction." (PMID 30038898, 2018). "They found that the inhibition of LONP1 could sensitize cancer cells to bortezomib, suggesting that targeting LONP1 may enhance the efficacy of proteasome inhibitors in cancer therapy." (PMID 40305312, 2025). "LONP1 is involved in metabolic reprogramming in cancer cells by remodeling the OXPHOS complex." (PMID 39261452, 2024). "LONP1 inhibitor CDDO has shown promising anti-cancer activity and it is compelling to speculate that the outcome could be influenced by the mitochondrial function of TFEB." (PMID 38263327, 2024). "LONP1 is also essential for the metastasis of cancer cells in vivo." (PMID 39261452, 2024). "Together with the fact that Sirt3 interacts with and deacetylates LONP1, Sirt3 may limit the transformation procedure in cancer initiation by maintaining appropriate lysosomal degradation of LONP1 through K63-ubiquitination pathway." (PMID 36739437, 2023). "In addition to worms, genetic or pharmacological inhibition of human LonP1 in cancer cells induces similar mitochondrial and cytoplasmic UPR mechanisms." (PMID 38139038, 2023).
cancer (continued). "These relationships might be evolutionarily conserved, as we have shown that genetic or pharmacological inhibition of human LonP1 in cancer cells induces the expression of genes involved in the heat shock response (HSR)." (PMID 38139038, 2023). "As LONP1 enhances mitochondrial functions for cancer cell survival, we developed a hypothesis that different constructs of LONP1 controls cell proliferation by modulating mitochondrial oxidative phosphorylation (OXPHOS)." (PMID 36739437, 2023). "Thus, in order to investigate if and how Lonp1 isoforms impact cancer progression, we performed a soft agar assay to highlight the possible differences in cell colony formation." (PMID 36497197, 2022). "Furthermore, triterpenoids that irreversibly suppress LonP1 activity have been found to induce apoptosis and inhibit cancer cell proliferation." (PMID 36362158, 2022). "Moreover, in several types of human tumors or cancer cell lines, LonP1 levels were increased, suggesting a high level of unfolded protein (proteotoxic) stress within mitochondria." (PMID 35456042, 2022). "However, the effects of LonP1 remain elusive, especially in different cellular microenvironments, such as those in inflammation, differentiation, primary carcinogenesis, and cancer metastasis." (PMID 36362158, 2022). "As previously shown, the expression of Lonp1 isoforms is highly variable in cancer cells of different origins, and this could suggest a different biological role for Lonp1 isoforms in cancer development and progression." (PMID 36497197, 2022). "LonP1 plays an important role in oncogenesis, cancer progression, and cancer cell invasion." (PMID 36362158, 2022). "In cancer, LonP1-triggered energy metabolic conversion is sometimes complicated." (PMID 36362158, 2022). "We found that LONP1 and ClpP cooperate to maintain protein quality and the activity of target substrates, which may support cancer cell proliferation and survival from cellular stress." (PMID 33637676, 2021). "Inhibition of LONP1 and ClpP separately reduces cancer growth and viability." (PMID 33637676, 2021). "There is increasing evidence that LONP1 and ClpP are involved in cancer." (PMID 33637676, 2021). "Despite functional similarities between LONP1 and ClpP in cancer, their regulatory mechanisms are largely unknown." (PMID 33637676, 2021). "However, LonP1 is expressed at high levels in specific cancers such as cervical, lung, bladder, colon cancer, and acute myeloid leukemia." (PMID 33922062, 2021). "Furthermore, co-expression of both proteins at high levels in multiple tumor types was associated with shortened patient survival, strongly supporting a functional link between LONP1 and ClpP in human cancer." (PMID 33637676, 2021). "For instance, Lonp1 and Txn2 are frequently induced by various stimuli in the cell, including hypoxia and the production of reactive oxygen species (ROS), and can therefore regulate cancer cell apoptotic resistance." (PMID 31061415, 2019). "In humans, mutations of the LonP1 gene are associated with a broad spectrum of diseases, including a rare multisystem developmental disorder known as CODAS (Cerebral, Ocular, Dental, Auricular, and Skeletal anomalies) syndrome, as well as neurodegeneration and cancer." (PMID 38139038, 2023). "This evidence suggests that LonP1 may be a potential target for cancer therapy." (PMID 35456042, 2022). "Indeed, inhibition of LONP1 mediated by triterpenoids leads to alterations in normal mitochondrial morphology and dysregulation of mitochondrial function, which ultimately triggers the death of cancer cells." (PMID 35180892, 2022). "Finally, we questioned the effect of LonP1 disruption on cancer cell motility." (PMID 35456042, 2022).
cancer (continued). "In this context, pharmacological targeting of LONP1 may represent an intriguing and unexplored way to indirectly impact on CI stability and consequently cancer cell metabolism, also considering that the protease inhibition has been found effective to selectively induce apoptosis in cancer cells." (PMID 34606156, 2022). "More importantly, LONP1 participates in ferroptosis by regulating the peroxidase GPX4 and NRF2/Keap1 signaling pathways, providing a cancer treatment strategy via ferroptosis." (PMID 39261452, 2024). "During anoxia, LONP1 is upregulated by HIF-1α, and its enzyme activity is enhanced by the cytochrome c oxidase (COX), thereby facilitating cancer cell adaptation to anoxic environments." (PMID 39261452, 2024). "Elevated LonP1 expression is correlated with progressive TNM staging, severe histological grading, and high cancer aggressiveness." (PMID 36362158, 2022). "In addition, the LonP1-ROS axis stimulates inflammatory factor generation and triggers epithelial-to-mesenchymal transition, angiogenesis, and M2 macrophage polarization, thereby leading to the growth of an immunosuppressive tumor microenvironment that encourages cancer development and metastasis." (PMID 36362158, 2022). "The following sections will discuss the known cancer-specific roles of ATF5 and key UPRmt proteins downstream of ATF5: HSP60, HSP10, mtHSP70, LONP1, and ClpP." (PMID 35864539, 2022). "Consistent with the cellular effects of LONP1 and ClpP inhibition, depletion of SHMT also reduced cancer cell growth and survival under cytotoxic stress conditions." (PMID 33637676, 2021). "Furthermore, depletion of LONP1 and ClpP increased cell sensitivity to an SHMT2 inhibitor, suggesting that SHMT2 is a key substrate in the LONP1- and ClpP-mediated proteostasis network and that its protein quality control by mitochondrial proteases may promote cancer cell survival and progression." (PMID 33637676, 2021). "Consistent with an increased sensitivity to cellular stress after LONP1 and ClpP knockdown, we observed that inhibition of SHMT2 enhanced cancer cell sensitivity to stressors such as oxidative stress (H2O2) or starvation (low glucose)." (PMID 33637676, 2021). "In cancer cells, LonP1 regulates the electron transport chain complex of the oxidative phosphorylation pathway that includes NDUFS8, which modulates the cancer stress phenotype and promotes cancer cell survival." (PMID 36362158, 2022). "Since we found significant differences in the colony formation between the cells overexpressing Lonp1 isoforms and normal cells, we hypothesized the possible different roles of Lonp1 isoforms in EMT, a known process involved in cancer progression." (PMID 36497197, 2022). "To this end, we have used two cell lines belonging to different types of cancer bearing-unlike characteristics, but both overexpressing LonP1." (PMID 35456042, 2022). "Therefore, it is presumable that the differential proliferating ability of cancer cells and neurons would lead to the distinct effects of CDDO-Me and LONP1 siRNA on neuronal damage." (PMID 31387295, 2019). "Thus, we wondered if the expression of Lonp1 isoforms could be different in cancer cells if compared to normal, non-transformed cells." (PMID 36497197, 2022). "However, details are lacking as to the mechanisms by which increased LonP1 expression might alleviate proteotoxic, hypoxic, and oxidative stress and reprograms mitochondrial energetics and metabolism in cancer growth and how these functions can be exploited for chemotherapeutic benefit." (PMID 35151690, 2022).
tumor (25 papers, 2018 to 2025). "The accumulated LONP1, elevated oxidative phosphorylation and glycolysis increase the risk of carcinogenesis and accelerate the growth of tumor." (PMID 36739437, 2023). "Collectively, these results indicate that VHL-null ccRCC cells are sensitized to sorafenib when combined with LONP1 inhibitor bortezomib, leading to a profound tumour growth defect in vivo that was associated with increased levels of mitochondrial content." (PMID 35760869, 2022). "An enhanced protease activity of Lonp1, caused by Akt-mediated phosphorylation, contributes to primary and metastatic tumour growth in vivo." (PMID 36497197, 2022). "Even though the function of LonP1 in tumorigenesis is still poorly understood, inhibition of the protease is likely associated with decreased rates of tumor cell growth, proliferation, and metastasis." (PMID 35456042, 2022). "LONP1 knockdown causes mitochondrial metabolic dysfunction and reduces tumor proliferation by impairing OXPHOS capacity." (PMID 35269393, 2022). "Further experiments revealed that LONP1 negatively regulates the nuclear factor E2-related factor 2/Kelch-like ECH-associated protein 1 (Nrf2/Keap1) signalling pathway to affect tumour growth." (PMID 34503532, 2021). "Additionally, it uncovered an innovative mechanism underlying how LONP1 contributes to tumor metastasis via its regulation of MPC1." (PMID 39971909, 2025). "Conversely, compared to the control group, overexpression of exogenous LONP1 significantly enhanced cell proliferation, colony formation, migration, and invasion, all of which are intimately linked with the promotion of malignancy in tumor cells." (PMID 39971909, 2025). "We observed a loss of Sirt3 and a concomitant elevation of LONP1 in tumor samples." (PMID 36739437, 2023). "In addition, the high expression of LonP1 can cause the downregulation of ACO2 activity in tumor cells." (PMID 36362158, 2022). "A higher expression of LonP1 has been associated with higher tumour aggressiveness." (PMID 36497197, 2022). "Additionally, LonP1 is implicated in a wide range of regulatory cellular processes, such as mitochondrial DNA maintenance, mitochondrial unfolded protein response, the metabolic adaptation of tumor cells, or stress adaptation of Drosophila melanogaster." (PMID 35456042, 2022). "The Lon protease 1 (LONP1) has been shown to promote glycolytic reprogramming of tumor cells, conferring a malignant proliferative phenotype." (PMID 40332105, 2025). "We have found that the tumor-promoting effects of LONP1 are primarily attributed to metabolic reprogramming, particularly the activation of a metabolic switch from OXPHOS to aerobic glycolysis in PCa cells." (PMID 39971909, 2025). "LONP1 promoted tumor cell proliferation and invasion by remodeling mitochondrial electron transport chain (ETC) complexes to mediate glycolytic reprogramming." (PMID 40332105, 2025). "Knockdown of LONP1 reduced tumor growth and metastasis in vivo, whereas overexpression enhanced them." (PMID 40332105, 2025). "In contrast to Pten−/− mice developing PIN, Lonp1 knockin resulted in the rapid acceleration of tumor progression." (PMID 39971909, 2025). "This contributes to providing novel insights into the tumor-promoting role of LONP1 and establishing mechanistic foundations for LONP1-targeting therapies." (PMID 39971909, 2025). "Mechanistically, the findings reveal that LONP1 is implicated in modulating the metabolic switch from oxidative phosphorylation (OXPHOS) to aerobic glycolysis, thereby promoting tumor proliferation, invasion, and metastasis both in vitro and in vivo." (PMID 39971909, 2025). "Our study provides vital new insights into the role of LONP1 as a facilitator of tumor progression in PCa." (PMID 39971909, 2025). "The results showed that, compared to the control group, the stable knockdown of LONP1 significantly decreased the tumor volumes and weights." (PMID 39971909, 2025).
tumor (continued). "LONP1 has been demonstrated to be highly expressed in many tumor types and promotes the malignant behavior of tumor cells by affecting various oncoproteins." (PMID 39971909, 2025). "LONP1 ablation also blocks tumor metastasis by inhibiting EMT and extracellular matrix remodeling through the c-Jun N-terminal kinase (JNK) pathway in human pancreatic cancer." (PMID 39261452, 2024). "Lonp1 induces tumor metabolic reprogramming and promotes inflammatory cytokine production generating an immunosuppressive tumor environment." (PMID 38882057, 2024). "Under the conditions of artificial induction of colon carcinoma, Lonp1+/– mice show lower tumor incidence and milder symptoms than wild-type mice." (PMID 39261452, 2024). "DUSP1 expression was decreased in tumor tissue whereas TNF, NOX4, and LONP1 expressions were increased in tumor tissue, compared with those in normal tissue." (PMID 38758860, 2024). "LONP1-K145Q further augmented tumor growth, whereas LONP1-K145R sharply regressed tumor progression as compared to LONP1-WT construct." (PMID 36739437, 2023). "Collectively, the acetylation status of LONP1 advances tumor growth and invasion via promoting OXPHOS." (PMID 36739437, 2023). "LONP1 deacetylation restricts tumor cell viability by reducing the energy supply of OXPHOS which was confirmed by a subcutaneous tumor mouse model." (PMID 36739437, 2023). "The LONP1 hyperacetylation-mutant K145Q enhances oxidative phosphorylation to accelerate tumor growth, whereas the deacetylation-mutant K145R produces calorie-restriction like phenotype to restrain tumorigenesis." (PMID 36739437, 2023). "Correspondingly, LONP1-K145Q enhance ATP production and LONP1-K145R reduce ATP content, suggested that the different construct of LONP1 governs tumor growth through regulating the energy metabolism, respectively." (PMID 36739437, 2023). "LONP1 maintains a bioenergetic and biosynthetic phenotype which is required for carcinogenesis, which illuminates that LONP1 knockdown lowered the activities of complex I and generated less ATP to leash tumor progression." (PMID 36739437, 2023). "LONP1 has been found to be involved in tumor metabolic reprogramming, which is related to remodeling the components of the ETC and antagonizing cellular senescence." (PMID 35180892, 2022). "For instance, the silencing of LONP1 causes mitochondrial metabolic dysfunction, cellular senescence, and reduced tumor formation via remodeling of the oxidative phosphorylation complex, whereas overexpression of LONP1 promotes tumorigenesis." (PMID 33637676, 2021). "Considering that LonP1 has been involved in controlling tumor bioenergetics by reprogramming mitochondrial functions, we analyzed mitochondrial activity by monitoring OCR." (PMID 30038898, 2018). "It has been reported that LonP1 controls tumor bioenergetics by remodeling subunits of electron transport chain." (PMID 30038898, 2018). "More recent evidence suggests that LonP1 is responsible for additional functions critical to tumor progression, including metabolic adaptation to hypoxia, protection against senescence, and resistance to apoptosis and oxidative stress." (PMID 30038898, 2018). "Starting from our previous observations, we aimed at investigating the precise role of LonP1 in colon primary tumor and metastasis." (PMID 30038898, 2018). "BT317 defines an emerging class of LonP1 and CT-L inhibitors that exhibited promising anti-tumor activity and could be a potential candidate for malignant astrocytoma therapeutics." (PMID 40088962, 2025). "Starting from the observation that LONP1 expression closely correlates with adverse clinicopathological features and poor prognosis in patients with PCa, our study here underscored that the elevated LONP1 expression promotes tumor progression and metastasis both in vitro and in vivo." (PMID 39971909, 2025). "ATF5, Hsp60, mtHsp70, Lonp1, and Clpp are upregulated in cancer, favoring tumor growth." (PMID 38882057, 2024).